INS (insulin)
Diseases named in the same sentence as INS in open-access papers (continued):
Sharing a sentence is not in itself a finding about the gene and the disease.
diabetes (continued). "In contrast, patients with diabetes that received insulin had similar adjusted combined rates of mortality and major complications as those not receiving insulin (adjusted OR=1.01; 95% CI 0.52-1.98; P=0.975)." (PMID 33118731, 2020). "In epidemiological studies, patients with diabetes and an eGFR < 60 ml/min/1.73 m2 have reduced insulin requirements." (PMID 33328554, 2020). "The top 50 diseases included “Obesity” (p = 1.24 × 10−13), “Diabetes” (p = 2.68 × 10−10), “Diabetes Mellitus, Non-Insulin-Dependent” (p = 3.79 × 10−10), and “Diabetes Mellitus” (p = 6.43 × 10−9)." (PMID 32709145, 2020). "In type 2 diabetes mellitus, the tissue resistance to insulin leads to hyperinsulinemia, and the physiologic level of insulin is not effective in controlling the serum glucose level." (PMID 32095207, 2020). "A large number of studies on the pharmacological effects of puerarin have shown that puerarin can improve glucose tolerance and insulin sensitivity in the animal model of type 2 diabetes mellitus (T2DM)." (PMID 32946041, 2020). "Free radicals destroy the ability of β-cells to secrete insulin and increase the incidence of diabetes complications." (PMID 33202817, 2020). "The current study was aimed at highlighting the role of blood pancreatic amylase in the regulation of glucose homeostasis and insulin secretion in a porcine model of streptozotocin- (STZ-) induced diabetes and in a rat pancreatic beta-cell line, BRIN-BD11." (PMID 33294459, 2020). "Visfatin is a pro-inflammatory adipokine with the ability to mimic insulin, and its circulating levels positively correlate with insulin resistance, metabolic syndrome, diabetes, and cardiovascular disease." (PMID 32660156, 2020). "While diabetes/insulin-resistance and breast cancer are distinct diseases, insulin-signaling plays a central role in both illnesses." (PMID 32153503, 2020). "A single peripheral injection of FGF1 in diabetic rodents normalizes diabetes within hours, while multiple doses promote insulin sensitization in as short as 3 weeks." (PMID 32372975, 2020). "Currently, the use of insulin and hypoglycemic drugs and cytokine-based therapeutics are the main and effective treatments for diabetes." (PMID 32131831, 2020). "Only three patients with steroid-induced diabetes exacerbation died, all from respiratory distress, while diabetes was correctly controlled with insulin." (PMID 33326457, 2020). "A link between disrupted brain insulin signaling and PD has been suggested by an increased rate of subsequent PD following type 2 diabetes mellitus in a large cohort study." (PMID 33216462, 2020). "HR were 0.91 (0.78–1.05) for SG and 1.19 (1.00–1.42) for MAs (GBP as reference), 0.96 (0.95–0.97) for diabetes duration, 0.58 (0.43–0.79) for insulin treatment, 0.92 (0.90–0.96) for HbA1c and 1.01 (1.02–1.20) for weight loss at 1 year." (PMID 32283783, 2020). "The FDS2 participants were older, more likely to be male, had longer diabetes duration and were, thus, more likely to be insulin-treated, and they consumed more alcohol." (PMID 33114323, 2020). "It was proposed that the TRP metabolites impact diabetes through different mechanisms, which can compromise either the insulin activity or insulin secretion." (PMID 32456137, 2020). "The transport of the SMA-insulin through biological membranes was assessed in vitro using Caco-2 cells, ex vivo rat intestinal section, and in vivo in a streptozotocin-induced diabetes mouse model." (PMID 33120872, 2020). "Preoperatively, 26 (29.2%) patients had diabetes: 18 patients (20.2%) were insulin dependent, 5 (5.6%) were on oral antidiabetics and 3 (3.4%) were following an antidiabetic diet." (PMID 33126342, 2020). "Of those patients with a prior diagnosis of diabetes, 8 (7.8%) patients were on a basal insulin regimen and 6 (5.8%) patients were on basal-bolus insulin regimen." (PMID 33284130, 2020).
diabetes (continued). "Excess Ac-CoA has been also observed in diabetes patients as insulin negatively regulates gluconeogenese by suppressing Ac-CoA." (PMID 32034223, 2020). "Body weight, food or water intake, blood glucose, and insulin levels are key clinical indicators of diabetes." (PMID 32143429, 2020). "Univariate analyses comparing those who did not develop MDD with those who did found that the mean length of follow-up was the same; however, they were more likely to be female and taking insulin for their diabetes." (PMID 32484148, 2020). "There is an evidence that longer duration of diabetes and need for insulin supplementation prior to the surgery correlate negatively with the chance for complete diabetes remission after the bariatric procedure." (PMID 33298009, 2020). "In response to the recent rise in numbers of diabetes patients, many treatments have been developed; but currently, oral antihyperglycemic agents and insulin are still the main clinical treatments." (PMID 32509879, 2020). "On the other hand, Type 2 diabetes mellitus is as a result of an individual's resistance to insulin with an insulin secretory defect." (PMID 32855973, 2020). "The etiology of Diabetes involves both insulin resistance and decreased insulin secretion in β cells." (PMID 33067534, 2020). "Several studies have shown that intensive insulin therapy can improve the function of islet β-cells, alleviate clinical symptoms of some patients, reduce diabetes-related complications, and improve the long-term prognosis of patients with T2DM." (PMID 33015194, 2020). "Although urodynamic determinations were not performed as part of this study, a large‐scale study published by our laboratory in 2009 investigated the effects of diabetes and insulin treatment on bladder function in the same rat model of T1D used here." (PMID 33200530, 2020). "The patients with a long duration of diabetes were more often treated with insulin than the other patients." (PMID 32758235, 2020). "A 43-year-old man was diagnosed with diabetes and initially well-controlled with oral hypoglycemic agents but progressed to requiring insulin within 1 year of diagnosis." (PMID 32982980, 2020). "Type-2 Diabetes Mellitus (T2DM) is a chronic disease characterized by chronic hyperglycemia derived from either impaired insulin secretion or impaired insulin action or both." (PMID 32204303, 2020). "Diabetes mellitus (DM), a highly prevalent and heterogeneous metabolic disorder, is characterized by dysregulation of insulin secretion and insulin action leading to disturbances in basal metabolism and chronic hyperglycemia, the key hallmark of the disease." (PMID 33367177, 2020). "As the normal balance between calorie intake and insulin secretion is disrupted in diabetes, the effectiveness of therapeutic fasting to reverse insulin resistance has been demonstrated." (PMID 32604970, 2020). "Diabetes mellitus (DM) is a chronic metabolic disorder commonly characterized by high blood glucose levels, resulting from defects in insulin production or insulin resistance, or both." (PMID 33274235, 2020). "This case is focused on the distribution of insulin, which is a vital product for people with chronic diseases such as pancreatic insufficiency or diabetes." (PMID 33816979, 2020). "A complete comprehension of the signaling pathways involved in the control of insulin release under different physiologic conditions should provide new insights to understand the pathophysiology of diabetes." (PMID 32934005, 2020). "Because diabetes mellitus is very common and insulin preparations are widely used, there is interest in understanding these underlying mechanisms in further detail." (PMID 35515176, 2020). "Since smoking is highly prevalent in diabetes and shares the same target organ as inhaled insulin, it should be researched for the long term in diabetic patients or a more generalizable population sample." (PMID 32850233, 2020).
diabetes (continued). "Current AI technologies applied to diabetes education mainly focus on diabetes prediction, lifestyle guidance, insulin injection guidance, blood sugar monitoring, self-management, and complication monitoring." (PMID 32548087, 2020). "The IDF Europe categories also mention that such apps should help people with diabetes make food choices, undertake carbohydrate and calorie counting, and calculate medication dosages (similar to an insulin bolus calculator)." (PMID 32678798, 2020). "Insulin is a potent growth factor that can increase ALL cell proliferation in vivo, and adults with diabetes are at increased risk for many cancers, including leukemia." (PMID 32706183, 2020). "Of the 1 084 052 participants with diabetes in the 4 health care systems, 223 908 had a first fill of insulin from January 1, 2005, through December 31, 2013." (PMID 31977057, 2020). "Considered together, these results indicate that dietary mulberry leaf administration can maintain insulin levels and pancreatic β-cell mass, at least in part, by suppressing endoplasmic reticulum stress in Type 2 diabetes mellitus mouse models." (PMID 32375753, 2020). "Recent results confirm that human α-cells are able to secrete insulin and reverse diabetes, but surprisingly, these cells express α-cell markers." (PMID 32477262, 2020). "For a global evaluation of adherence, including items such as physical exercise, blood glucose testing, insulin use, and diet, the Diabetes Self-Management Profile seems to be better for assessing adherence in children and adults with type 1 diabetes." (PMID 32236314, 2020). "In this GSMR model, we used 59, 79 and 79 SNPs as the instrumental variables in diabetes, glucose and insulin models, respectively." (PMID 32612641, 2020). "In terms of treatment, it was striking that only 2% of the patients at the diabetes clinic received insulin." (PMID 32814520, 2020). "In obesity, adipose tissue becomes dysfunctional, promoting a pro-inflammatory, hyperlipidemic and insulin resistant environment that contributes to type 2 diabetes mellitus (T2DM)." (PMID 32158768, 2020). "Chrysophanol targets significantly decrease blood lipids, serum insulin levels in diabetes, and reduces inflammatory cytokines, myocardial enzymes creatine kinase (CK) and lactate dehydrogenase (LDH), and increases SIRT1 protein expression." (PMID 33287318, 2020). "These patients were more likely to have diabetes (76.4% vs. 59.8%, p < 0.001), hypertension (79.4% vs. 75.2%, p = 0.002), obesity (56.1% vs. 45.7%, p < 0.001), and intraoperative insulin administration (55.7% vs. 6.6%, p < 0.001)." (PMID 32381036, 2020). "From a pathophysiological standpoint, in the regulation of the carcinogenic process in patients with diabetes, specific alterations in both microRNAs and long non-coding RNAs affecting insulin signalling have been described." (PMID 32708201, 2020). "In respect of diabetes therapies, insulin and sulphonylureas (SUs) have been identified as conveying mortality hazard in a number of observational studies." (PMID 32256448, 2020). "Mainly, management of diabetes are limited to two pharmacological interventions such as insulin its related analogous and oral anti-diabetic agents." (PMID 32815547, 2020). "The basal component, insulin degludec, exhibits flat and stable steady-state pharmacokinetic and pharmacodynamic profiles in patients with diabetes." (PMID 32290465, 2020). "Interest in the potential ability of cinnamon to control glucose in diabetes management increased after the discovery of a bioactive insulin-potentiating agent initially identified as hydroxychalcone derived from cinnamon." (PMID 33553233, 2020). "Liraglutide was prescribed to 68 obese type two diabetes patients with uncontrolled diabetes taking more than one oral medication ± insulin." (PMID 32292448, 2020). "Peroral antidiabetics (PADs) and insulin are long-term standards of care for patients with diabetes mellitus." (PMID 33585194, 2020).
diabetes (continued). "Polyphenols play an important role in the control of diabetes by inhibiting the absorption of glucose from small intestine, enhancing the secretion of insulin and the controlled release of glucose from liver." (PMID 32971839, 2020). "Induction of diabetes by STZ caused significant increase in FBS (P-value<0.05), and insulin treatment in the diabetic group as well as encapsulated INPs significantly ameliorated the blood glucose (P-value<0.05)." (PMID 32695298, 2020). "Before surgery, 28.5% of the patients had diabetes (10.4% insulin treated and 18.1% non-insulin treated), 23.3% dyslipidemia, and 34.5% hypertension." (PMID 32806629, 2020). "Diabetes mellitus (DM) is a serious, chronic disease that occurs either by impaired insulin secretion or insulin resistance or both." (PMID 32456637, 2020). "The education program should be developed and generalized to Muslims with diabetes, at least for insulin-dependent participants." (PMID 33226993, 2020). "While insulin has been available for treating diabetes for almost a century now, to date, the most common insulin therapy is to be administered to diabetic patients through the parenteral route." (PMID 33066443, 2020). "The induction of diabetes reduced the expression of these molecules, and insulin re-established their expression levels." (PMID 32117245, 2020). "Diabetes mellitus results from the impaired secretion of insulin with variable degrees of peripheral insulin resistance leading to hyperglycemia." (PMID 32244716, 2020). "One hundreds male rats were randomly divided into seven groups: the control, diabetes, insulin (Ins)." (PMID 32405365, 2020). "Direct associations were found between brain age difference and metabolic traits such as type I (OR 2.39, 95% CI 1.73–3.29) and type II (OR 1.42, 95% CI 1.25–1.61) diabetes and participants taking insulin (OR 2.22, 95% CI 1.55–3.14)." (PMID 33203906, 2020). "This study finding is limited in its generalizability in patients with T2D on insulin pharmacotherapy and have greater severity of diabetes-related complications." (PMID 33253259, 2020). "Several hypoglycaemic agents singly or in combination with insulin are clinically used to treat type 2 diabetes mellitus." (PMID 32210082, 2020). "Increased insulin levels in patients with diabetes, as shown in our study, are among the important factors for stimulating ANGPTL8 production." (PMID 32746907, 2020). "It has been shown that adiponectin acts as a diabetes regulating hormone that activates the autophagy pathway in insulin target cells and decreases in metabolic diseases." (PMID 33041786, 2020). "Among 46 patients with data available on diabetes treatment, the largest percentage was treated with oral medication alone (n = 20, 43%), followed by insulin (n = 16, 35%) and diet modification (n = 7, 15%)." (PMID 33437503, 2020). "The DM type II (DMT-II) is the most abundant form of diabetes and generally involves the phenomenon of insulin insensitivity or low insulin production." (PMID 32103043, 2020). "In the selection of the variables for multivariable analysis, there was weak evidence of multicollinearity between diabetes status and insulin treatment (r = 0.49; variance inflation factor = 1.32)." (PMID 33328554, 2020). "Maternal prepregnancy body mass index, insulin-treated pregestational diabetes, and pregestational type 2 diabetes and gestational diabetes without insulin treatment." (PMID 32031649, 2020). "The prospect of identifying spectral biomarkers in saliva open new perspectives for monitoring the severity of diabetes, and compliance with insulin treatment modalities." (PMID 32182246, 2020). "In the context of diabetes and obesity, adequate mitochondrial calcium uptake is fundamental for insulin-mediated glucose uptake." (PMID 32630236, 2020). "Diabetes is an age-related metabolic disorder involving insulin secretion abnormalities and defects due to the action of insulin against its target tissues." (PMID 33269108, 2020).
diabetes (continued). "The goal of this review was to present a balanced view of the utility of insulin treatment of diabetes mellitus." (PMID 33167495, 2020). "Self-titration of insulin is well established in type 1 diabetes, but for most patients with type 2 diabetes, dose titration is still carried out by physicians and diabetes nurse specialists." (PMID 32406854, 2020). "High levels of leptin in the HFD mice and increased plasma glucose, insulin and IGF-1 in the serum indicated leptin resistance and insulin resistance, suggesting the onset of diabetes." (PMID 32639947, 2020). "People living with human immunodeficiency virus and diabetes were mostly female, older, had type 2 DM, had increased BMI and were mainly on insulin monotherapy when compared to PLWHD." (PMID 33240534, 2020). "MNAM can effectively reduce levels of fasting blood glucose and insulin, improve liver morphology, and reduce lipid accumulation in obese type 2 diabetes mellitus mice." (PMID 32280711, 2020). "Regression analysis with independent variables (FBS, duration of diabetes and insulin use) showed similar results (P = 0.031)." (PMID 32308951, 2020). "In this respect, substantial experimental and clinical work has been implemented to evaluate the efficacy of autologous stem cells in the management of hyperglycemia and insulin sensitivity in diabetes patients." (PMID 32294623, 2020). "We also detected pathways related to diabetes (i.e., insulin secretion, insulin resistance, and type II diabetes mellitus)." (PMID 31875662, 2020). "For example, in 1922, a Canadian orthopedic surgeon and his medical student discovered insulin, a breakthrough in the practice of medicine that revolutionized the therapy of diabetes." (PMID 32117664, 2020). "Diabetes mellitus is a metabolic disorder that is characterized by chronic hyperglycemia resulting from insufficient insulin secretion and/or insulin resistance in target tissues." (PMID 32903738, 2020). "Despite the higher insulin levels in diabetic subjects, diabetes mellitus is accompanied by lower serum concentrations of melatonin in diabetic GotoKakizaki rats." (PMID 32280378, 2020). "In pre-diabetes and compromised metabolic states such as obesity, insulin resistance, and glucose intolerance, beta cells biosynthesize and secrete more insulin, i.e., hyperfunction." (PMID 33182622, 2020). "Some foods in this dietary pattern, including refined grains, white bread, biscuits, and sweets, led to a rapid increase in postprandial plasma glucose, insulin concentration, and diabetes." (PMID 32605646, 2020). "Oral L-glutamine enhances the circulation of gastrointestinal incretin hormones (glucagon-like peptide-1 (GLP-1) and stimulated insulin release as well as reduced (postprandial) glycemia in diabetes mellitus." (PMID 32983244, 2020). "Some of the other problems reported by homeless people with diabetes include difficulties in exercising, scheduling and prioritising diabetes over other problems, securing insulin needles and other medications." (PMID 33095271, 2020). "Conversely, in another study, a participant reported that they had stopped using insulin to treat their diabetes, after being advised by their older sister that they would become dependent on the medication." (PMID 32908858, 2020). "In patients with diabetes, treatment with metformin and a-glucosidase inhibitors is associated with a reduced risk of developing CRC, whereas insulin has been shown to promote CRC." (PMID 33187505, 2020). "In our study, ucOC positively correlated with insulin secretion independently of BMI in Japanese individuals with diabetes." (PMID 32821293, 2020). "Diabetes mellitus (DM) is a group of chronic metabolic disorders characterized by the elevation of blood glucose levels (hyperglycemia) due to defects in insulin secretion and/or activity." (PMID 32956382, 2020).